ITCH (itchy E3 ubiquitin protein ligase)
Diseases named in the same sentence as ITCH in open-access papers (continued):
Sharing a sentence is not in itself a finding about the gene and the disease.
glioma (7 papers, 2018 to 2022). A benign or malignant brain and spinal cord tumor that arises from glial cells (astrocytes, oligodendrocytes, ependymal cells). "Furthermore, decreased cir-ITCH level was associated with poor survival of glioma patients, by sponging miR-214 and regulating ITCH-Wnt/β-catenin pathway." (PMID 30018188, 2018). "Research shows that circ-ITCH exerts a tumor-suppressive function upon glioma cells through the miR-106a-5p/SASH1 axis and miR-214/ITCH-Wnt/β-catenin pathway." (PMID 35327551, 2022). "In glioma, circITCH exerts anti‐oncogenic effects via miR‐214 sponging and modulating the ITCH‐Wnt/β‐catenin pathway." (PMID 35274492, 2022). "Through miR-214 inactivation and modulation of ITCH-Wnt/β-catenin axis in glioma cells, cir-ITCH upregulation can improve apoptosis." (PMID 35111757, 2021). "Cir-ITCH dramatically enhanced glioma cell proliferation, migration, and invasion." (PMID 35883576, 2022). "In glioma tissues and cell lines, cir-ITCH expression was decreased." (PMID 35883576, 2022). "Similarly, in glioma cells, cir-ITCH plays a tumor-suppressive role by sponging miR-214 to increase ITCH protein expression and modulate the Wnt/b-catenin cascade." (PMID 34162394, 2021). "Therefore, restoration of cir-ITCH expression could be a future direction to develop a novel treatment strategy in ESCC and glioma." (PMID 30018188, 2018).
breast tumors (5 papers, 2014 to 2025). "The nuclear localization of ITCH, as upregulated in breast tumors, is a result of pS257, where nuclear ITCH prolongs transcriptional activity, influences cell replication, and promotes tumor progression." (PMID 35327659, 2022). "In TNBC, circ-ITCH exhibits breast tumor inhibition and can promote the expression of ITCH tumor suppressor by absorbing miR-214 and miR-17." (PMID 31526370, 2019). "Collectively, these data demonstrate that ITCH cooperates with RAS to accelerate breast tumor growth in vivo." (PMID 25350971, 2014). "The E3-ligase ITCH plays a crucial role during the development of breast tumors." (PMID 40136647, 2025).
lung adenocarcinoma (5 papers, 2019 to 2025). A carcinoma that arises from the lung and is characterized by the presence of malignant glandular epithelial cells. "Human lung adenocarcinoma epithelial cells (A549) treated with shRNA against the E3 ligase ITCH (HECT-type ubiquitin E3 ligase) revealed that there was more viral RNA (vRNA) in the cytoplasm of ITCH knockdown cells, as compared to the control." (PMID 33652634, 2021). "In addition, proteins such as ASS1, ITCH, or UBE2L3 involved in pathways related to the inhibition of a particular molecular background could be used as potential response biomarkers, thereby improving the efficacy of this therapeutic approach to combat lung adenocarcinoma." (PMID 37762133, 2023).
pancreatic cancer (5 papers, 2016 to 2025). "Collectively, these results indicate that ITCH is of paramount importance in regulating in vivo pancreatic cancer metastatic progression and does so by inhibiting Hippo signaling and promoting nuclear translocation of YAP." (PMID 26621835, 2016). "To explore the expression of miR-106b and ITCH in human pancreatic cancer, we determined miR-106b expression in 20 pancreatic cancer patients, 10 with high ITCH and 10 with low ITCH expression." (PMID 26621835, 2016). "Given that our experiments indicated a role of ITCH in in vivo tumorigenesis and metastatic progression and hsa-miR-106b mediated regulation of ITCH, we hypothesized that suppression of hsa-miR-106b expression might be an underlying feature of human pancreatic cancer." (PMID 26621835, 2016). "Here we report that ITCH transcript and protein expression mimic metastatic trait in pancreatic cancer patients and cell lines." (PMID 26621835, 2016). "Functional consequence of ITCH expression on pancreatic cancer metastasis was confirmed using in vivo animal models of experimental metastasis." (PMID 26621835, 2016). "We furthermore show that hsa-miR-106b, which itself is down regulated in metastatic pancreatic cancer, directly interacts and inhibit ITCH expression." (PMID 26621835, 2016). "In summary, we have shown that ITCH over expression and has-miR-10b down regulation are potential novel biomarkers for predicting poor prognosis for human pancreatic cancer." (PMID 26621835, 2016). "In the present study, we analyzed LATS1 and ITCH expression in pancreatic tumor tissue specimens compared to normal pancreatic tissue specimens and correlated the expression levels to overall survival and percent disease progression." (PMID 26621835, 2016). "For example, short-term activation of JNK may increase the viability and growth of pancreatic cancer cells, whereas long period of activation may result in cell apoptosis such as through the E3 ubiquitin ligase ITCH-induced c-FLIPL turnover." (PMID 30584464, 2018). "We next determined if ITCH is a bona fide target of hsa-miR-106b in pancreatic cancer cell lines." (PMID 26621835, 2016). "ITCH and hsa-miR-106b are thus potential biomarkers for pancreatic cancer prognosis." (PMID 26621835, 2016). "It needs to be determined if ITCH plays a role in pancreatic cancer tumorigenesis also or whether its function is limited to metastatic progression." (PMID 26621835, 2016). "We next wanted to determine what dictates ITCH overexpression in pancreatic cancer tissues." (PMID 26621835, 2016). "The results indicated that ITCH protein expression mimicked the metastatic (or mesenchymal state) of the cells and also gave us a model system where the role of ITCH and mechanism of its regulation in pancreatic cancer could be further investigated." (PMID 26621835, 2016). "USP9X, a deubiquitinase for ITCH, is focally repressed in pancreatic cancer (PDAC), leading to reduced ITCH protein levels and aggressive PDAC phenotypes." (PMID 39851497, 2025). "The level of ITCH and LATS1 expression were determined in 30 paired pancreatic cancer samples and matched adjacent, histologically normal tissues by qRT-PCR, and normalized to TBP expression (internal control)." (PMID 26621835, 2016). "We next determined that has-miR-106b targets ITCH transcript and that differential expression of has-miR-106b determines expression level of ITCH in non-metastatic and metastatic pancreatic cancer cell lines and patients." (PMID 26621835, 2016). "We next determined the steady state LATS1 and ITCH protein expression levels in the non-metastatic pancreatic cancer cell line, BxPC-3 and the metastatic pancreatic cancer cell line, PANC-1." (PMID 26621835, 2016). "However, the role of ITCH in pancreatic cancer progression has not been described." (PMID 26621835, 2016).
pancreatic cancer (continued). "However, levels of ITCH expression, its correlation to LATS1 levels and function, and its regulation has not yet been established in the context of pancreatic cancer." (PMID 26621835, 2016).
papillary thyroid cancer (5 papers, 2022 to 2024). "Furthermore, it was discovered that circ-ITCH plays a pivotal role in impeding the progression of papillary thyroid carcinoma (PTC) through its influence on the circ-ITCH/miR-22-3p/CBL axis." (PMID 39130630, 2024). "Moreover, miR-22-3p is reported to participate in circ-ITCH-mediated regulation in the development of papillary thyroid cancer." (PMID 38730434, 2024). "In addition to ITCH protein, circ-ITCH can also suppress papillary thyroid cancer development and progression by acting as the sponge of miR-22-3p and regulating the miR-22-3p/CBL/Wnt/β-catenin pathway." (PMID 35327551, 2022).
neuroblastoma (4 papers, 2011 to 2024). Neuroblastoma (NB) is the most common solid, extracranial childhood tumor. "Overexpression of ITCH leads to the degradation of the LAPTM5 protein, while inhibition of ITCH enhances LAPTM5 accumulation in neuroblastoma cells, leading to increased cell death." (PMID 39281638, 2024). "Our study provides evidence that ITCH can be effectively silenced in neuroblastoma both in vitro and in vivo." (PMID 31974512, 2020). "In conclusion, we have shown that silencing of ITCH by siRNA significantly induced apoptosis of Kelly neuroblastoma cells upon irradiation." (PMID 31974512, 2020). "ITCH has been shown to ubiquitinate over 50 target proteins, and ITCH depletion leads to increased p73 levels and increased sensitivity to radiation therapy in neuroblastoma cells." (PMID 37957138, 2023). "Similarly, ITCH mediates ubiquitination of the Hrs protein, suggesting further interactions between UBE4B and ITCH may occur on the endosomal membrane surface and contribute to the associations of UBE4B expression with neuroblastoma patient outcomes." (PMID 37957138, 2023). "In mouse N2A neuroblastoma cells, miR-125b significantly downregulated mouse BAK1, PPP1CA, PUMA, and ITCH protein." (PMID 21935352, 2011). "Transfection of these cell lines with ITCH siRNA could effectively silence the ITCH expression, and result in the stabilization of TP73 protein, which mediated the apoptosis of the neuroblastoma cells upon irradiation treatment." (PMID 31974512, 2020).
triple-negative breast carcinoma (4 papers, 2019 to 2025). An invasive breast carcinoma which is negative for expression of estrogen receptor (ER), progesterone receptor (PR), and human epidermal growth factor receptor 2 (HER2). "Here, we demonstrate a mechanism through which a distinct E3 ubiquitin ligase, ITCH, modulates DDR machinery in triple-negative breast cancer (TNBC)." (PMID 30517763, 2019).
asthma (3 papers, 2021 to 2025). "For example, Ndfip1 encodes a regulatory protein that enhances the activity of the ubiquitin ligase ITCH to negatively regulate inflammation and has been associated with asthma risk in GWAS studies." (PMID 40326866, 2025). "For example, Ndfip1 encodes a regulatory protein that enhances activity of the ubiquitin ligase ITCH to negatively regulate inflammation and has been associated with asthma risk in GWAS studies." (PMID 38712036, 2025). "Previous papers have shown that the E3 ligases Cbl-b, ITCH, and TRIM18 are associated with inflammation in asthma." (PMID 34903714, 2021).
atherosclerosis (3 papers, 2015 to 2024). A disease characterized by the build-up of fatty material and calcium deposition in the arterial wall resulting in partial or complete occlusion of the arterial lumen. "In this study, our primary focus was on investigating the role and underlying mechanism of ITCH in endothelial ferroptosis within the context of atherosclerosis." (PMID 39769287, 2024). "Here we investigate the role of ITCH deficiency on the development of atherosclerosis." (PMID 25777360, 2015). "We therefore investigated the effect of ITCH deficiency on the development of atherosclerosis." (PMID 25777360, 2015). "We herein show for the first time that the loss of ITCH results in a reduced development of atherosclerosis coupled with reduced hepatic fatty infiltration in the hypercholesterolemic ApoE−/− mouse model through reduced clearing of SREBP2 and SIRT6 respectively." (PMID 25777360, 2015). "Therapeutic targeting of ITCH-FTL pathway components has the potential to be against atherosclerosis." (PMID 39769287, 2024). "Given that dysfunction of endothelial cells is pivotal in the early stages of lesion development, the objective of this study is to elucidate the biological significance of ITCH in endothelial ferroptosis during atherosclerosis." (PMID 39769287, 2024). "ITCH plays a role in regulating lipid metabolism, which in turn influences the advancement of atherosclerosis by controlling the ubiquitination of SIRT6 and SREBP2 in the liver." (PMID 39769287, 2024). "Together, these results robustly imply that ITCH significantly contributes to the advancement of atherosclerosis." (PMID 39769287, 2024). "The E3 Ubiquitin Ligase ITCH modulates lipid metabolism impacting on atherosclerosis progression independently from effects on myeloid cells polarization through control of SIRT6 and SREBP2 ubiquitination." (PMID 25777360, 2015). "However, ITCH’s role in atherosclerosis has been insufficiently explored, particularly concerning vascular cell mechanisms." (PMID 39769287, 2024). "Additionally, in vivo experiments showed that inhibiting ITCH reduced atherosclerosis progression and reversed ferroptosis in the aorta, with an associated increase in FTL protein expression in the aortas of mice." (PMID 39769287, 2024). "The levels of ITCH protein in the aortas of mice with atherosclerosis were analyzed." (PMID 39769287, 2024). "Additionally, the in vivo experiments in this study demonstrated that inhibiting ITCH reduced the progression of atherosclerosis and reversed ferroptosis in the aorta, accompanied by increased FTL protein expression in the aortas of mice." (PMID 39769287, 2024). "This indicates that ITCH contributes to aortic ferroptosis during atherosclerosis progression." (PMID 39769287, 2024). "This also suggests that ITCH may influence atherosclerosis progression through other mechanisms." (PMID 39769287, 2024). "Hence, we hypothesize that ITCH might influence vascular cell ferroptosis in atherosclerosis." (PMID 39769287, 2024). "The findings suggest that the beneficial effects of ITCH suppression on atherosclerosis are at least partially due to inhibiting the ITCH-FTL axis, with ITCH-mediated ubiquitination of FTL contributing to endothelial ferroptosis in atherosclerosis." (PMID 39769287, 2024). "This research seeks to investigate the function and fundamental mechanisms of Itchy E3 ubiquitin ligase (ITCH), a HECT (homologous to E6AP carboxyl terminus)-type E3 ubiquitin ligase, in endothelial ferroptosis, particularly in the context of atherosclerosis, which has been underexplored." (PMID 39769287, 2024).
autoimmune disease (3 papers, 2014 to 2020). A disorder resulting from loss of function or tissue destruction of an organ or multiple organs, arising from humoral or cellular immune responses of the individual to their own tissue constituents. "A bi-allelic mutation in ITCH gene was observed to cause a severe syndromic multisystem autoimmune disease." (PMID 32365888, 2020). "In human, in addition to multisystem autoimmune diseases akin to the Itchy mice phenotype, patients with ITCH mutations displayed morphologic and developmental abnormalities." (PMID 25369329, 2014).
inflammatory bowel disease (3 papers, 2019 to 2024). A spectrum of small and large bowel inflammatory diseases of unknown etiology. "Mutations in ITCH cause inflammation, including inflammatory bowel disease or nephritis, and the ITCH deficiency is associated with multisystem autoimmune disease." (PMID 31623112, 2019).
thyroid cancer (3 papers, 2020 to 2022). "The level of circ-ITCH is closely associated with clinical stage, lymph node metastasis, and patient prognosis in thyroid cancer." (PMID 35513849, 2022). "Circ-ITCH exerts its tumor suppressor action by modulating miR-22-3p/CBL/β-catenin in thyroid cancer." (PMID 35513849, 2022). "CircRNA_102171 and circRNA_NEK6 are relatively upregulated, while circ-ITCH is downregulated in thyroid cancer tissues and cell lines." (PMID 35513849, 2022). "Additionally, dysfunctional circRNAs like circ-ITCH, circRAPGEF5, circ_0025033, circZFR and circRNA_102171, was also found in thyroid cancer, indicating the critical contribution of circRNAs in thyroid cancer pathogenesis." (PMID 35135416, 2022). "For example, circRNA_NEK6 could regulate proliferation and invasion of thyroid cancer by targeting miR-370-3p; circZFR facilitated thyroid cancer cell proliferation and invasion by sponging miR-1261; circ-ITCH restrained thyroid cancer progression by miR-22-3p." (PMID 32082079, 2020).
viral infection (3 papers, 2020 to 2024). "Indeed, genetic or pharmacological inhibition of ITCH significantly decreased the replication of SARS-CoV-2, indicating that ITCH may be a promising target for the development of treatments for the viral disease." (PMID 39677672, 2024). "In this regard, yeast two-hybrid screens identify poly rC binding protein 1 (PCBP1) and PCBP2 as positive regulators of the interaction between ITCH/AIP4 and MAVS, whose levels are increased upon viral infection." (PMID 32117959, 2020). "Consistently, without SARS-CoV-2 infection, ITCH ablation does not exhibit involvement in the maturation of CTSL processing in vT2 cells, further implying that ITCH does not affect the CTSL-dependent virus infection process." (PMID 39677672, 2024).
Autoimmunity (2 papers, 2019 to 2025). The occurrence of an immune reaction against the organism's own cells or tissues. "AD STAT5b deficiency: growth-failure and eczema without immune defects; (iii) AD STAT1 GOF CMC and autoimmunity; (iv) AR ITCH deficiency: autoimmunity, dysmorphic facial features and neurodevelopmental delay." (PMID 39945219, 2025).
cardiac hypertrophy (2 papers, 2021 to 2022). "Overall, ITCH may be a therapeutic target for cardiac hypertrophy." (PMID 34199773, 2021). "ITCH potentially mediates the degradation of non-Dvl substrates during cardiac hypertrophy; therefore, further studies are needed to clarify the effect of ITCH on other substrates during cardiac hypertrophy." (PMID 34199773, 2021).
cervical cancer (2 papers, 2020 to 2024). A primary or metastatic malignant neoplasm involving the cervix. "We demonstrate that ITCH promotes loss of gap junctions in cervical cancer cells, which is associated with increased degradation of Cx43 in lysosomes." (PMID 38597989, 2024). "Our study suggests that ITCH negatively controls the size of gap junctions in cervical cancer cells by promoting the lysosomal degradation of Cx43 and thereby reducing the cellular pool of Cx43 available to form gap junctions." (PMID 38597989, 2024). "Taken together, the data identify ITCH as a novel regulator of gap junction intercellular communication and may have implications for our understanding of the post-translational mechanisms involved in mediating the loss of this form of cell-cell communication during cervical cancer pathogenesis." (PMID 38597989, 2024). "In the present study, evidence is provided that ITCH interacts with Cx43 and regulates its ubiquitination in cervical cancer cells." (PMID 38597989, 2024). "Thus, the finding that ITCH interacts with Cx43 and targets it for degradation in cervical cancer cells may be an important step toward understanding the molecular basis underlying the loss of Cx43-based gap junctions during cervical cancer pathogenesis." (PMID 38597989, 2024). "Next, we examined whether ITCH regulates the Cx43 protein level and gap junction size in cervical carcinoma cells expressing Cx43 endogenously." (PMID 38597989, 2024).
chronic lymphocytic leukemia (2 papers, 2016 to 2021). "It has been previously indicated that ITCH mRNA may be targeted by hsa-miR-106b in chronic lymphocytic leukemia patients." (PMID 26621835, 2016).
glioblastoma (2 papers, 2019 to 2025). The most malignant astrocytic tumor (WHO grade IV). "Other studies identified JNK1/2 as the main regulator of ITCH-induced c-FLIP degradation after TNFα stimulation or AKT inhibition in glioblastoma." (PMID 31443721, 2019).